DNAJC27 (DnaJ heat shock protein family (Hsp40) member C27)
Description:
GTPase which can activate the MEK/ERK pathway and induce cell transformation when overexpressed. May act as a nuclear scaffold for MAPK1, probably by association with MAPK1 nuclear export signal leading to enhanced ERK1/ERK2 signaling.
Synonyms: RABJS; RBJ
Tractability: No criterion of Open Targets' tractability assessment is met for any kind of drug.
Gene: Protein-coding gene on chromosome 2 (24,943,636 to 24,972,094, reverse strand). Ensembl gene ENSG00000115137.
Subcellular location: Nucleus
Subcellular location (Human Protein Atlas): Cytosol
Gene Ontology:
Molecular function: protein binding; GTP binding; GTPase activity
Biological process: positive regulation of ERK1 and ERK2 cascade
Cellular component: nucleus; cytoplasmic vesicle
Genetic constraint (gnomAD): Loss-of-function variants: 11 observed, 22.78 expected, observed/expected ratio (o/e) 0.48, 90% interval 0.3 to 0.8. The upper end of that interval is the gene's LOEUF score, 0.8, which puts it in group 3 of 6, group 1 being the genes least tolerant of losing a copy. Missense variants: 251 observed, 266.69 expected, observed/expected ratio (o/e) 0.94, 90% interval 0.85 to 1.04. Synonymous variants: 76 observed, 88.66 expected, observed/expected ratio (o/e) 0.86, 90% interval 0.71 to 1.04.
Homologues: Orthologues: chimpanzee DNAJC27 (100% identical), macaque DNAJC27 (99% identical), dog DNAJC27 (96% identical), pig DNAJC27 (96% identical), guinea pig DNAJC27 (93% identical), mouse Dnajc27 (93% identical), rabbit DNAJC27 (87% identical), rat Dnajc27 (86% identical), tropical clawed frog dnajc27 (86% identical), zebrafish dnajc27 (84% identical). Paralogues in human: RAB26 (25% identical), RAB6A (25% identical), RAB6B (25% identical), RAB7A (25% identical), RAB37 (25% identical), RAB6D (25% identical), RAB18 (24% identical), RAB40B (24% identical), RAB6C (24% identical), RAB13 (24% identical), RAB21 (24% identical), RAB40AL (24% identical), and 56 more.
Diseases named in the same sentence as DNAJC27 in open-access papers:
DNAJC27 is named in the same sentence as 5 diseases in open-access papers, as found by Europe PMC text mining. Sharing a sentence is not in itself a finding about the gene and the disease. The quoted sentences say what the papers report.
Obesity (5 papers, 2018 to 2024). Accumulation of substantial excess body fat. "Another gene associated with increased adiposity in global genome-wide association studies is DNAJC27, a heat shock protein known to be elevated in obesity." (PMID 32733386, 2020). "The causal genes might be ADCY3 and DNAJC27, which have previously been identified to be related to obesity and pubertal growth, respectively." (PMID 30271426, 2018). "Little is known regarding the role of DNAJC27 in obesity and T2D." (PMID 30131766, 2018). "Knowing that DNAJC27 is involved in the activation of ERK in cancer, it is possible that it plays a role through the MAPK pathway affecting stress response and inflammation which in turn plays a role in the pathogenesis of obesity." (PMID 30131766, 2018).
lung squamous cell carcinoma (1 paper, 2020). "For example, DNAJC9 was upregulated in 8 cancer types, including bladder urothelial carcinoma (BLCA), stomach adenocarcinoma (STAD), and lung squamous cell carcinoma (LUSC), while DNAJC27 was downregulated in 9 cancer types, including LUAD, kidney renal clear cell carcinoma (KIRC) and BRCA." (PMID 33225964, 2020).
tumor (2 papers, 2016 to 2018). "However, a recent investigation of the human member of the family, RBJ (or DNAJC27 according to the official human gene nomenclature), showed that it is a nuclear protein interacting with protein kinases and has a possible role in tumor progression." (PMID 26832778, 2016).
DNAJC27 also shares sentences with these, for which no sentence is quoted: cancer (2 papers); Inguinal hernia (1).